MTOR (mechanistic target of rapamycin kinase)
Diseases named in the same sentence as MTOR in open-access papers (continued):
Sharing a sentence is not in itself a finding about the gene and the disease.
osteosarcoma (continued). "Sorafenib has shown clinical activity in osteosarcoma, both as single agent and in combination with mammalian target of rapamycin (mTOR) inhibitors." (PMID 34069999, 2021). "The aim was to investigate changes in autophagic activity and the molecular mechanism of Notch1-mediated PI3K/Akt/mTOR signalling during autophagy to provide a theoretical basis for the treatment of osteosarcoma." (PMID 34495871, 2021). "Aloin inhibited the proliferation of osteosarcoma by inhibiting the PI3K/AKT/mTOR pathway, increasing autophagic flux and promoting the apoptosis of osteosarcoma cells." (PMID 34819120, 2021). "mTOR inhibition has been proposed as an attractive therapeutic approach, given the mTOR/PI3K mutations promoting proliferation and metastasis while inhibiting apoptosis in osteosarcoma cell models." (PMID 33917001, 2021). "Previous studies confirm that hyperactivation of the AKT/mTOR signaling pathway contributes to tumorigenesis, and leads to aberrant tumor growth and invasion, especially in osteosarcoma." (PMID 34185412, 2021). "Subsequent studies verified that aloin mediated the autophagic flux increase and osteosarcoma apoptosis through the PI3K/AKT/mTOR axis." (PMID 34819120, 2021). "This indicated that aloin induced autophagy and apoptosis of osteosarcoma through the PI3K/AKT/mTOR pathway in vivo." (PMID 34819120, 2021). "The mammalian target of rapamycin (mTOR) has also been a target of interest in osteosarcoma; however, single-agent studies of mTOR inhibitors have failed in osteosarcoma trials." (PMID 33503424, 2021). "For example, P2X7 activates the phosphatidylinositol 3-kinase/AKT/mTOR pathway and other signaling pathways to promote the proliferation and metastasis of osteosarcoma and increase bone destruction." (PMID 34759265, 2021). "The lack of rapamycin activity in this system correlates with literature demonstrating that mTOR inhibitors combined with other agents have had limited clinical efficacy in osteosarcoma." (PMID 33503424, 2021). "Studies have shown that MMP-2 and MMP-9 are involved in AKT/mTOR-mediated invasion and metastasis of osteosarcoma cells." (PMID 34953496, 2021). "Recent studies have shown that the PI3K/AKT/mTOR signaling pathway is widely activated in osteosarcoma cells, especially in the drug resistant osteosarcoma cells." (PMID 34953496, 2021). "On the contrary, the combined treatment with JQ1 and the mTOR inhibitor rapamycin synergistically inhibited growth and survival of osteosarcoma cells both in vitro and in vivo experiments." (PMID 34440844, 2021). "Therapeutic effects, autophagy enhancement and regulatory effects on the PI3K/AKT/mTOR pathway were demonstrated in a nude mouse xenogeneic osteosarcoma transplantation model." (PMID 34819120, 2021). "OIP5-AS1 induced cisplatin resistance in osteosarcoma through regulating the LPAATβ/PI3K/AKT/mTOR signaling pathway via a mechanism involving miR-340-5p." (PMID 33821219, 2021). "The HSP90i geldanamycin induces autophagy via inhibition of AKT/mTOR signaling in osteosarcoma cells." (PMID 33743824, 2021). "To address these possibilities, as well as the potential involvement of NRF2 in the SFN-mediated inhibition of mTOR, in this study we used the human osteosarcoma cell line U2OS and its CRISPR/Cas9-generated NRF2-knockout counterpart." (PMID 31409554, 2021). "Thirdly, a nine-year old female with first local and metastasic osteosarcoma relapse with positive mTOR immunochemistry was treated with an oral mTOR inhibitor during a two-month period after failure of standard treatments." (PMID 33916788, 2021). "Some reports indicate that activation of the AKT/mTOR signaling pathway plays an important role in the progression of osteosarcoma and cisplatin resistance." (PMID 34953496, 2021). "Numerous studies have identified that TGF‐β and AKT/mTOR signaling pathways were extremely relevant to the biological process of osteosarcoma." (PMID 34185412, 2021).
osteosarcoma (continued). "Better understanding of how Notch1 regulates PI3K/Akt/mTOR would likely create novel therapeutic opportunities for targeting these important cellular pathways in osteosarcoma." (PMID 34495871, 2021). "We suggest that chemotherapeutic agents induce autophagy in a SESN2-dependent manner by downregulating mTOR phosphorylation, which further promotes the inhibition of chemotherapeutic drug-induced apoptosis of osteosarcoma cells." (PMID 34646824, 2021). "The increase of cisplatin resistance in osteosarcoma can be achieved by inducing PI3K / Akt / mTOR signaling pathway by OIP5-AS1." (PMID 33272245, 2020). "Further studies suggested that IOP can also inhibit the activation of the Akt/mTOR and NF-κB signaling pathway in osteosarcoma cells." (PMID 33282634, 2020). "In osteosarcoma, activation of mTOR signaling (phosphorylation) accelerated cellular metastasis and presented an unfavorable prognosis through the regulation of downstream targets." (PMID 32054506, 2020). "Activated mTOR contributes to osteosarcoma transformation and indicates a poor prognosis; it functions through downstream effectors such as eIF4, 4EBP1, and S6K142." (PMID 32944406, 2020). "MicroRNA-22 mediates the cisplatin resistance of osteosarcoma cells by inhibiting autophagy via the PI3K/Akt/mTOR pathway." (PMID 33272245, 2020). "In an attempt to increase sorafenib’s activity, the authors concurrently supressed mTOR, which had been shown to inhibit tumour growth in osteosarcoma mouse models." (PMID 32961800, 2020). "The results of this study indicate that polysaccharide from Inonotus obliquus polysaccharide can regulate the proliferation, migration, invasion, and apoptosis of osteosarcoma cells by inhibiting the activation of the Akt/mTOR and NF-κB signaling pathway." (PMID 33282634, 2020). "Cheng and colleagues have reported that suppression of BZW2 exists inhibitory effects on osteosarcoma growth in part by the regulation of the Akt/mTOR signaling pathway." (PMID 33005104, 2020). "It is a central controller in many important cellular functions, and many cancers, including osteosarcoma, have an abnormally high activity of mTOR." (PMID 32961800, 2020). "Many preclinical studies have confirmed the efficiency of PI3K/AKT/mTOR pathways-targeted chemicals on chemo-resistant osteosarcoma; however, only a few mTOR-targeted compounds succeeded in entering clinical trials currently." (PMID 32404870, 2020). "Another study performed by Cheng and colleagues also suggested that suppression of BZW2 had inhibitory effects on osteosarcoma growth in part by the regulation of the Akt/mTOR signaling pathway." (PMID 33005104, 2020). "In previous work, we demonstrated that zoledronic acid was effective in reducing Ras farnesylation and Akt/mTOR activation in human and murine osteosarcoma cells." (PMID 32155954, 2020). "The deregulation of the mTOR signaling pathway had been reported to be involved in various pathological diseases and tumor progression, including osteosarcoma." (PMID 32054506, 2020). "IOP can regulate the proliferation, migration, invasion, and apoptosis of osteosarcoma cells by inhibiting the activation of the Akt/mTOR signaling pathway." (PMID 33282634, 2020). "Calycosin (#2) acts on the PI3K/AKT/mTOR pathway, blocking tumor growth and inducing apoptosis in an estrogen receptor-positive osteosarcoma cell line." (PMID 32041350, 2020). "Recently, BZW2 has been recognized to be involved in the osteosarcoma by the regulation of Akt/mTOR signaling pathway." (PMID 33005104, 2020). "The mammalian target of rapamycin (mTOR) as a serine or threonine protein kinase has been reported to contribute to the development and progression of human cancers, including osteosarcoma." (PMID 30847386, 2019). "The effect and significance of mTOR had been previously studied in various areas in the literature such as neurofibromatosis, rotator cuff tears, pathologies of nucleus pulposus, and osteosarcoma." (PMID 31655537, 2019).
osteosarcoma (continued). "In this study, we confirm that LHX2 is up-regulated in osteosarcoma, and that its silencing inhibits OS malignancy and induces autophagy via mTOR signaling." (PMID 31724536, 2019). "In conclusion, our results reveal that DADs induced G2/M arrest, apoptosis, and autophagic death of human osteosarcoma cells by inhibiting the PI3K/Akt/mTOR signaling pathway." (PMID 31340526, 2019). "EEF1D is upregulated in osteosarcoma and plays a tumor promoting role by facilitating Akt-mTOR and Akt-Bad signaling pathways." (PMID 29510727, 2018). "Taken together, these results allowed us to conclude that TSSC3 overexpression induces autophagy in osteosarcoma cells by inactivating the Src-mediated PI3K/Akt/mTOR pathway." (PMID 30092789, 2018). "Then, we showed that TSSC3 overexpression enhanced autophagy via inactivating the Src-mediated PI3K/Akt/mTOR pathway in osteosarcoma." (PMID 30092789, 2018). "And also, Akt/mTOR pathway is critical for tumor distant metastasis in osteosarcoma mouse model and cultured cells." (PMID 29492195, 2018). "Collectively, these results indicate that PRDX1 promotes osteosarcoma invasion and metastasis through enhancing Akt/mTOR pathway." (PMID 29492195, 2018). "Upon phosphorylation, activated mTOR contributed to osteosarcoma cellular transformation and poor prognosis." (PMID 29510727, 2018). "Deregulation of the PI3K/Akt/mTOR pathway is associated with osteosarcoma progression 9 and mTOR and PI3K are essential for osteosarcoma proliferation and survival." (PMID 29744300, 2018). "Taken together, we demonstrated, for the first time, that TSSC3 induces autophagy via inhibiting the Src-dependent PI3K/Akt/mTOR pathway in osteosarcoma." (PMID 30092789, 2018). "We found that reduction in EEF1D downregulated the Akt-mTOR and Akt-Bad signaling pathways in osteosarcoma cells." (PMID 29510727, 2018). "Biological pathways implicated in osteosarcoma biology through genetic and other preclinical studies include PI3K/mTOR, WNT/βcatenin, TGFβ, RANKL/NF-κB, and IGF." (PMID 29435436, 2018). "Mechanistically, EEF1D exerts oncogenic effects by maintaining the Akt-mTOR and Akt-Bad signaling pathways in osteosarcoma." (PMID 29510727, 2018). "A slight decrease in the phosphorylation of Akt-Thr308, mTOR-Ser2448 and Bad-Ser112 was detected in these osteosarcoma cell lines." (PMID 29510727, 2018). "It has also been demonstrated that CX treatment for 72 h induced autophagy and altered mTOR signaling in osteosarcoma cell lines." (PMID 28774889, 2017). "MTOR signaling, a known downstream effector of amino acid metabolism and a target for novel agents in relapsed paediatric tumours, was enriched within osteosarcoma for both OTC and ARG2." (PMID 28969007, 2017). "ZA also acts synergistically with mTOR inhibition to decrease proliferation of murine and human osteosarcoma cell lines in vitro and to reduce osteosarcoma tumor growth in two distinct syngeneic murine modals." (PMID 27127605, 2016). "Further supporting these comprehensive analyses, the use of novel genetic screening technologies provides additional evidence for the importance of the PI3K/mTOR pathway in osteosarcoma." (PMID 27441088, 2016). "Heuristic analysis of whole genome, exome, and RNA sequencing data from 59 osteosarcoma tumors revealed alterations in the PI3K/mTOR pathway in 24% of samples that included aberrations ofPTEN,TSC2, PIK3R1, PIK3CA, and several other genes." (PMID 27441088, 2016). "On the other hand, the cell-permeable short chain C6 ceramide enhanced pemetrexed-induced apoptosis and cytotoxicity in osteosarcoma cells through inhibition of Akt-mammalian target of rapamycin (mTOR) signaling." (PMID 27043542, 2016). "A phase II study of the mTOR inhibitor ridaforolimus included two osteosarcoma patients with a confirmed partial response and one patient with an unconfirmed partial response." (PMID 27441088, 2016).
osteosarcoma (continued). "In the present study, we investigated the activity of XL388, a novel mammalian target of rapamycin (mTOR) complex 1/2 (mTORC1/2) dual inhibitor, in preclinical osteosarcoma (OS) models." (PMID 27385099, 2016). "Notablely, rapamycin reduces tumor cell metastasis in a murine model of osteosarcoma via blocking the mTOR/S6K1/4E-BP1 pathway." (PMID 27177330, 2016). "Recently, growing researches show aberrant activation of mTOR in many cancer including human osteosarcoma." (PMID 27177330, 2016). "The following brief review will highlight recent analyses supporting the role of PI3K/mTOR inhibition as an area ripe for further exploration in osteosarcoma." (PMID 27441088, 2016). "The study suggests that in osteosarcoma, resistance to sorafenib is mediated, at least partly, through the mTOR pathway." (PMID 27501793, 2016). "Activity of dual PI3K/mTOR inhibitors was subsequently observed in cell death assays of cultures from primary human xenograft-derived osteosarcoma (GSK2126458, PKI-587, BEZ-235, and BGT-226)." (PMID 27441088, 2016). "Several recent complementary genomic and pathway analyses of both murine and human osteosarcoma have revealed common aberrations of the phosphoinositide 3-kinase (PI3K)/mammalian target of rapamycin (mTOR) pathway in osteosarcoma." (PMID 27441088, 2016). "When considered in their broader context, our observations indicate that mTOR-targeting represents a promising way to improve the treatment of high-grade osteosarcoma, especially those characterized by the presence of highly immature SSEA-4+ TICs." (PMID 25853231, 2015). "In relation to miRNAs in this context, miR-223 is thought to have a tumour-suppressing role through the PI3K/Akt/mTOR pathway in osteosarcoma." (PMID 26204834, 2015). "The expression of mTOR is correlated with event-free survival and cancer progression in osteosarcoma." (PMID 26807203, 2015). "The correlation of miR-199a and the mTOR pathway is also confirmed in human osteosarcoma, in which transfection of precursor miR-199a acts tumor suppressive." (PMID 26251897, 2015). "Currently, there are several ongoing clinical trials using mTOR inhibitors in patients with osteosarcoma." (PMID 24216993, 2013). "Human osteosarcoma tissue samples have stained positive for mTOR signaling and this has been correlated with surgical stage, metastasis pattern, and disease-free survival." (PMID 23476113, 2013). "Our work supports an oncogenic role for mTORC1 activity in osteosarcoma and provides evidence to link mTOR signaling, ALDH activity, and metastatic behavior." (PMID 23476113, 2013). "In parallel, we realized Western blot with RAD-001 on chondrosarcoma and osteosarcoma cells concerning the major actors of the mTOR cell signalling pathways." (PMID 21437224, 2011). "mTOR is often aberrantly activated in cancers and, in particular in chondrosarcoma and osteosarcoma." (PMID 21437224, 2011). "Here, we showed that miRNA profiles of osteosarcoma cells were in accordance with their response to the mTOR inhibitor, RAD-001." (PMID 21437224, 2011). "Study data provide the basis to include the dog in the study of mTOR inhibitors as part of their development in pediatric osteosarcoma and other cancers." (PMID 20543980, 2010). "Many questions remain regarding the optimal use of mTOR inhibitors in cancer and in pediatric osteosarcoma in particular." (PMID 20543980, 2010). "Therapeutic agents targeting mTOR have emerged as promising strategies for treating osteosarcoma." (PMID 40283955, 2025). "In conclusion, TRIM17 regulates FTO expression by promoting post-translational ubiquitination modification of FTO protein, thereby positively modulating the AKT/mTOR signaling pathway to enhance the clonability and survival potential, migration, and invasion of osteosarcoma." (PMID 41145484, 2025).
osteosarcoma (continued). "Mechanistically, TRIM17 promotes the ubiquitination and degradation of FTO protein, enhances PDK1 mRNA stability via N6-methyladenosine (m6A) modification, and subsequently promotes phosphorylation-dependent activation of the AKT/mTOR signaling pathway, thereby driving osteosarcoma malignancy." (PMID 41145484, 2025). "They found that the MAPK and PI3K/Akt/mTOR pathways could play an important role in the metastasis of osteosarcoma, which was targeted by Rh2." (PMID 40507179, 2025). "In osteosarcoma, hsa-miR-199a-3p is significantly underexpressed; its restoration suppresses tumor cell growth and migration by directly targeting oncogenes such as Met, mTOR, and Stat3." (PMID 41154751, 2025). "In osteosarcoma, Prkci promotes tumor cell growth by activating the Akt/mTOR pathway." (PMID 40840329, 2025). "HSP90B1 is a direct target of miR-223 and miR-223 may have a tumor suppressor function in osteosarcoma through the PI3K/Akt/mTOR pathway and could be used in anticancer therapies in osteosarcoma." (PMID 40831924, 2025). "This further is supported by in vitro work in osteosarcoma U2-OS cells, where loss of STAG2 is associated with decreased activation of the PI3K pathway, evidenced by decreased phosphorylation of PI3K, Akt, and mTOR." (PMID 40025053, 2025). "Furthermore, HSP90 has been implicated in chemotherapy resistance in osteosarcoma cells, where it inhibits apoptosis via the JNK/P38 pathway and promotes autophagy through the PI3K/Akt/mTOR pathway." (PMID 40227333, 2025). "However, a study has indicated that NTZ inhibits the activity of the AKT/mTOR and Wnt/β-catenin signaling pathways in osteosarcoma cells." (PMID 40446026, 2025). "GSEA analysis based on HSPD1 transcript expression from all osteosarcoma patients in the training and validation cohorts showed that the positively regulated gene set by mTOR signaling (MTOR_UP.N4.V1_UP) was enriched significantly in HSPD1-overexpressing cohorts." (PMID 39430254, 2024). "GSEA analysis based on HSPD1 transcript expression in osteosarcoma cohorts revealed that the gene set positively regulated by mTOR signaling (MTOR_UP.N4.V1_UP) was significantly enriched in the HSPD1-overexpressing cohorts, indicating that mTOR signaling is activated." (PMID 39430254, 2024). "Mechanistically, HSPD1 may interact with ATP5A1 to reduce the K48-linked ubiquitination and degradation of ATP5A1, which ultimately activates the AKT/mTOR pathway to ensure osteosarcoma progression and EMT process." (PMID 39430254, 2024). "Western blot analysis showed inhibitory activity on the expression of related proteins in the protein kinase B/mammalian target of rapamycin (Akt/mTOR) signalling pathway by IOP, indicating that the antitumor effect of IOP against osteosarcoma is through hindering Akt/mTOR activation." (PMID 38813471, 2024). "The mTOR pathway is also abnormally activated in many cancers, including human osteosarcoma." (PMID 38212768, 2024). "Finally, we explored the relationship between PRKCI and the Akt/mTOR signaling pathway in osteosarcoma cell lines." (PMID 39015499, 2024). "Similarly, ATP5A1 knockdown impaired mTOR phosphorylation in osteosarcoma cells, whereas ATP supplementation partially restored mTOR signaling." (PMID 39430254, 2024). "AIM2 inhibited the progression of osteosarcoma by inhibiting PI3K/AKT/mTOR signaling pathway." (PMID 39600708, 2024). "Additionally, PHLDA2 has been shown to impact EMT and metastasis in osteosarcoma through the SRC/PI3K/AKT/mTOR and WNT/GSK3-β/β-catenin signaling pathway." (PMID 38827322, 2024). "Finally, the protein molecule expression of the Akt/mTOR signaling pathway in osteosarcoma was detected when PRKCI was knocked down." (PMID 39015499, 2024). "ATP5A1 overexpression resulted in increased levels of p-AKT and p-mTOR in osteosarcoma cells." (PMID 39430254, 2024). "Moreover, DATS treatment led to the inactivation of the EGFR/PI3K/AKT/mTOR pathway in osteosarcoma cells." (PMID 38434350, 2024).